FOXP3 (forkhead box P3)
Diseases named in the same sentence as FOXP3 in open-access papers (continued):
Sharing a sentence is not in itself a finding about the gene and the disease.
hepatocellular carcinoma (continued). "However, in hepatocellular carcinoma (HCC), FOXP3 is associated with improved outcomes, where it may act through distinct pathways, such as modulating TGF-β/Smad signaling." (PMID 39883234, 2025). "For all these reasons, elevated levels of circulating CD4+ CD25+ FoxP3+ Tregs are associated with tumor progression and reduced survival rates in patients affected by hepatocellular carcinoma, and the FOXP3+ Treg/CD4+ T-cell ratio also serves as a prognostic indicator for overall survival." (PMID 38791916, 2024). "Moreover, inhibiting the IL‐6‐STAT3/Foxp3 cascade showed immune‐related antitumor effect in hepatocellular carcinoma, wherein IL‐6‐STAT3 signaling inactivation suppressed Foxp3 expression in Tregs." (PMID 36226375, 2023). "Interestingly, the proportion of GARP+/FoxP3+ Tregs is elevated in hepatocellular carcinoma and GARP is significantly upregulated in FoxP3+ Tregs in these patients." (PMID 34571713, 2021). "MiR‐23a was inversely correlated with CCL22 and Foxp3 in HBV+ hepatocellular carcinoma tissues." (PMID 31769216, 2020). "It has been reported that CD14+HLA-DR–/low M-MDSCs could induce CD4+CD25+Foxp3+Treg cells when co-cultured with autologous T cells in hepatocellular carcinoma (HCC) patients." (PMID 33384962, 2020). "Besides this mechanisms affecting overall cAMP levels, it has been shown that the repression of Foxp3 using siRNA in hepatocellular carcinoma patients induces a downregulation of CTLA-4 in those Treg with lower Foxp3 levels, compromising their function." (PMID 27242797, 2016). "In addition, high percentages of CD14+HLA-DR−/low M-MDSCs in patients with hepatocellular carcinoma were shown to induce the production of CD4+CD25+Foxp3+ regulatory T cells." (PMID 25436215, 2014). "Previous evidence has shown that the FOXP3 gene was involved in the pathogenesis of several tumors; however, the correlation between single nucleotide polymorphisms (SNPs) in the FOXP3 gene and the susceptibility to hepatitis B-related hepatocellular carcinoma (HCC) remains unclear." (PMID 23759077, 2013). "The authors found that lnc-EGFR was highly expressed in Treg cells and positively correlated with FOXP3 expression in hepatocellular carcinoma (HCC)." (PMID 37189549, 2023). "The GDF-15-CD48 interaction was shown to promote the propagation of Treg cells and indirectly upregulate forkhead transcription factor (Foxp3), enhancing the development of hepatocellular carcinoma (HCC)." (PMID 35251002, 2022). "Herein, we investigated the clinical relevance and biological significance of FOXP3 expression in human hepatocellular carcinoma (HCC)." (PMID 28903735, 2017). "However, through our systematic review and meta-analysis, we got a more unified conclusion that CD3+, CD4+, CD8+, and Foxp3+ could serve as prognostic biomarkers in hepatocellular carcinoma." (PMID 28790445, 2017). "In fact, in hepatocellular carcinoma, mRNA alterations in the FKH region of Foxp3 influenced its subcellular localization and altered its function." (PMID 37766222, 2023). "A prior study identified Foxp3+ Treg cells expressing a characteristic human NK cell marker (i.e., CD56) in cancer tissues of hepatocellular carcinoma patients." (PMID 36177042, 2022). "We found that peptide F393–403 was able to inhibit FOXP3:NFAT interaction and demonstrated that in vivo peptide administration had antitumor activity in a murine model of hepatocellular carcinoma." (PMID 33671179, 2021). "Recently, CD4+CD25+ Foxp3 Treg has been highlighted as playing a key immunosuppressive role in the cellular subpopulation of the tumor microenvironment in hepatocellular carcinoma (HCC), which is critical in both the development and spread of HCC." (PMID 34858499, 2021). "We found that peptide F393–403, a truncated version of peptide F393–407, inhibited FOXP3–NFAT interaction and improved effector T-cell functions in response to TCR stimulation and delayed tumor growth in a model of hepatocellular carcinoma." (PMID 33671179, 2021).
hepatocellular carcinoma (continued). "The status of FOXP3 and its isoforms in hepatocellular carcinoma (HCC) is unclear." (PMID 33116119, 2020). "The results of this study showed that solanine inhibited the growth of transplanted hepatoma in mice and reduced the proportion of CD4+CD25+Foxp3+ Treg and the expression levels of Foxp3 and TGFβ mRNA." (PMID 33204731, 2020). "In order to observe the effect of solanine on Treg in hepatocellular carcinoma-bearing mice, CD4+CD25+Foxp3+ was used as the marker of Treg in this study." (PMID 33204731, 2020). "In this study, we also found celecoxib administration can reduce FOXP3+ Tregs, CD68+ TAMs, and PD‐L1 expression and increase CD8+ CTLs in hepatoma tissues during epirubicin therapy." (PMID 29683262, 2018). "Interestingly, cyclization of the peptide improved very significantly its capacity to bind to FOXP3, to inhibit Treg in vitro, and more importantly, to delay tumor growth in combination with anti-PD1 antibodies in a model of hepatocellular carcinoma." (PMID 29069740, 2017). "As anticipated, tumour infiltrating FoxP3+ Treg have been reported to be negative prognostic factors for ovarian, esophageal and hepatocellular cancer." (PMID 19698134, 2009). "In the context of hepatocellular carcinoma (HCC), the TIL subpopulations most commonly studied include Foxp3+, CD8+, and CD4+ T cells, as well as B lymphocytes, NK cells, and macrophages, all of which are associated with prognostic outcomes." (PMID 40308592, 2025). "Meanwhile, it increased NK cells’ cytotoxicity in spleen, down-regulated the amount of CD4+CD25+Foxp3+ Treg cells and Th17 cells in tumor tissue, and decreased IL-10, TGF-β, and IL-17A levels (P < 0.01) whereas increased IL-2 and IFN-γ levels (P < 0.01) in the serum of hepatoma H22-bearing mice." (PMID 28086772, 2017). "Notably, multi-color immunofluorescence and confocal microscopy demonstrated that Tim-3+Foxp3+CD4+ cells were preferentially distributed in the tumor nest rather than the peritumoral stroma of hepatocellular carcinoma." (PMID 23526963, 2013). "As compared with the hepatocellular carcinoma (HCC) component, the lower density of CD8+ T cells and higher intensity of Foxp3+ Tregs and immune checkpoints in the intrahepatic cholangiocarcinoma (ICC) component may indicate a stronger immune evasive ability of ICC." (PMID 32508015, 2020). "By extension, if FOXP3+ Tregs showed no increase in patients with CHB and in the tumor environment after pre-treatment, sequential IL-2 therapy (combined with immune checkpoint blockade) may have an application in the eradication of tumors such as hepatocellular carcinoma." (PMID 34737296, 2021).
cervical carcinoma (87 papers, 2010 to 2026). A carcinoma arising from either the exocervical squamous epithelium or the endocervical glandular epithelium. "Only the FOXP3 T allele showed a strong association with cervical cancer patients, with an expression probability 3.37 times higher than in healthy individuals (OR: 3.37; p < 0.05)." (PMID 41263059, 2025). "Genetic polymorphism of HLA‐G and FOXP3 was assessed in 55 cervical cancer patients with clinical follow‐up, relapse, or death, and compared to 126 healthy controls." (PMID 41263059, 2025). "In cervical cancer, low expression of FOXP3 is associated with favorable prognosis, as it inhibits tumor progression by regulating Treg activity." (PMID 40517358, 2025). "Foxp3 and p16INK4a expressions elevate as cervical lesions progress, with Foxp3 expression being positively associated with p16INK4a expression in cervical cancer." (PMID 38790189, 2024). "The expression of CD28 and FOXP3 was highly correlated, and high expression of IDO1, FOXP3, CD28, and FOXP3 was all associated with improved survival in cervical cancer." (PMID 39672307, 2024). "TILs were also shown to have a beneficial effect in advanced cervical carcinoma as distinct infiltration of CD3+, CD4+, CD8+, CD206+ and FOXP3+ TILs were significantly associated with progression-free and overall survival in cervical cancer." (PMID 36612258, 2022). "In conclusion, Foxp3 is a risk factor for the survival of cervical cancer, which is consistent with our current findings." (PMID 33671013, 2021). "Nevertheless, it was reported that Foxp3 expression was associated with progression of cervical cancer." (PMID 32957741, 2020). "As shown in the regulatory network, TFs STAT1 and FOXP3 were involved in regulatory relationship with multiple IRGs for cervical cancer, while IRGs PGR and LTA were associated with multiple TFs for endometrial cancer." (PMID 32793281, 2020). "In this experiment, we investigated the association of Foxp3 with VEGF-C expression and the role of Foxp3 in lymphangiogenesis of cervical cancer." (PMID 28923073, 2017). "The present assay shows that Foxp3 expression is associated with advancement of cervical cancer and lymph node metastasis." (PMID 28923073, 2017). "Some studies even found that the number of tumor infiltrating Foxp3+Treg cells was completely associated with poor survival in several kinds of solid carcinoma such as ovarian and cervical cancers." (PMID 20064222, 2010). "Previous studies showed that TNFR2+ Tregs increased in tumors of cervical cancer patients, and Foxp3+ tumor infiltrating immune cells in the central tumor area might be a biomarker for risk stratification in cervical cancer patients." (PMID 34479503, 2021). "Foxp3 is associated with lymphangiogenesis of cervical cancer." (PMID 33671013, 2021). "Our study suggested that CD45RO+ TILs in the invasive margin area and FOXP3+ TILs in the central tumor area might be useful biomarkers for risk stratification in cervical cancer patients." (PMID 31616592, 2019). "From this IRG–TF regulatory network, we can see that in cervical cancer, FOXP3 positively regulates low-risk IRGs (LTA and PTPN6) and positively regulates low-risk IRGs (LTA) in endometrial cancer, suggesting that FOXP3 may act as a tumor suppressor in these two types of cancers." (PMID 32793281, 2020). "Furthermore, Foxp3 is associated with lymphangiogenesis of cervical cancer." (PMID 28923073, 2017). "Therefore Foxp3+ Treg cells up-regulation may be the underlying mechanisms of cervical cancer genesis and development." (PMID 23587428, 2013). "FOXP3 polymorphism, along with CXCL12‐CXCR4 axis and SNAIL upregulation in an oncogenic HPV/XPO5 TME with high M2‐TAM infiltration, critically influences cervical cancer patient survival." (PMID 41263059, 2025). "Previous studies have correlated high infiltration of FOXP3+ Tregs with poor prognosis across several tumor types, including gastric and cervical cancer." (PMID 40806346, 2025).
cervical carcinoma (continued). "Neoadjuvant chemotherapy has been shown to improve the immune microenvironment of cervical cancer by reducing the number of Foxp3+ T cells, thereby mitigating immunosuppressive effects and enhancing antitumor immune responses." (PMID 40539072, 2025). "In this study, we determined the diagnostic accuracy of serum P16ink4A and FOXP3 concentrations for detection of cervical intraepithelial neoplasia (CIN) and cervical cancer (CC) in a rural setting in Southwestern Uganda." (PMID 40365511, 2025). "While the improved survival of patients with increased expression of FOXP3 or IDO1 contradicts the role of T-cell suppression in cervical cancer, FOXP3 and IDO1 can be expressed in tumor cells." (PMID 39672307, 2024). "The expression of FOXP3 was also observed in tumor cells; in cervical cancer, FOXP3 increases as the tumor progresses." (PMID 36672296, 2023). "Tregs frequency in peripheral blood of 51 cervical cancer and 46 control participants was evaluated using Foxp3 as a specific marker for Tregs." (PMID 37670247, 2023). "A more recent study on infiltrating immune cells characterization showed that tumor-infiltrating lymphocytes in cervical cancers contain a higher proportion of FoxP3(+) T lymphocytes." (PMID 37894319, 2023). "The evidence so far supports that FOXP3 expression tends to increase in cervical cancer and HPV-positive cervical samples." (PMID 36672296, 2023). "We report a significant increase in the frequency of CD4 + CD25 + FoxP3 + T cells (Tregs) in the peripheral blood of cervical cancer participants." (PMID 37670247, 2023). "A significant increase in Treg frequency expressed as FoxP3 + Tcells as a proportion of CD4 + CD25 + cells was recorded in women with cervical cancer (11.00 ± 19.79%) compared to the controls (1.71 ± 8.91%), (p < 0.0001)." (PMID 37670247, 2023). "An increased density of CD8+, FoxP3+, and PD-1+ cells was observed in sentinel LNs, compared to distant LNs of 30 patients with cervical cancer." (PMID 36835583, 2023). "A recently published study suggested that the expression of FOXP3 is closely related to the occurrence and growth of cervical cancer." (PMID 36672296, 2023). "The expression of FOXP3 correlates with the prognosis of cervical cancer, and it is significantly higher in cancer than in cervical intraepithelial neoplasia or chronic cervicitis." (PMID 36672296, 2023). "The aim of this study was to investigate the effects of forkhead box protein P3 (FOXP3) intron single nucleotide variants (SNVs) in high‐risk human papilloma virus (HR‐HPV) infection and cervical cancer (CC) malignant lesions." (PMID 35322929, 2022). "This experiment established a mouse cervical cancer model to detect the levels of Foxp3 and VISTA, a T cell activation inhibitor, after CMNa sensitized radiotherapy." (PMID 33784955, 2021). "Our results suggest that FOXP3 has a different function in normal cervical tissue than in cervical cancer tissue." (PMID 35087740, 2021). "FoxP3 has been confirmed to be highly expressed in cervical cancer, and it facilitates the proliferation and invasiveness and inhibits the apoptosis of cervical cancer cells." (PMID 33671013, 2021). "Within a study of our group, we retrospectively analyzed the clinical significance of the expression of CCL22 and FOXP3 in 230 cervical cancer patients." (PMID 34833360, 2021). "Reports have suggested that FOXP3 upregulation heightens the degree of immune escape seen in cervical cancer cells." (PMID 34140005, 2021). "In cervical cancer tissue, it is known that FOXP3 expression is upregulated, however, little is known about FOXP3 expression in normal cervical tissue." (PMID 35087740, 2021). "Estradiol-bound ER alpha drives FOXP3 expression by binding with the FOXP3 promoter of Treg cell in both healthy male and in tumor microenvironment of cervical cancer patients." (PMID 34127827, 2021).
cervical carcinoma (continued). "The results showed that 53% of Tregs of cervical cancer were FoxP3+ or expressing TGF-β1 and IL-10, and they were able to inhibit the function of both Th (Th1 and Th2) subsets." (PMID 34553029, 2021). "As shown in, in cervical cancer tumor tissue, the levels of Foxp3 and VISTA in the four groups are significantly different." (PMID 33784955, 2021). "The level of IL-10 was decreased greatly in colorectal cancer and that of Foxp3 decreased in cervical cancer after ARS treatment." (PMID 33117153, 2020). "In cervical cancer, UFC1 upregulated FOXP3 expression through competitively binding miR-34a, promoting cervical cancer growth and metastasis." (PMID 32242003, 2020). "This study revealed a similar trend, that the protein level of CCL22 from both cervical cancer cells and infiltrating cells was positively correlated with FOXP3." (PMID 31842422, 2019). "This study retrospectively analyzed the clinical significance of the expression of CCL22 and FOXP3 in 230 cervical cancer patients." (PMID 31842422, 2019). "Tissue microarray by immunohistochemistry was performed to test the number of CCL22+ and FOXP3+ cells in a retrospective cohort of 230 cervical cancer cases, including 187 cases of squamous carcinoma and 43 cases of adenocarcinoma." (PMID 31842422, 2019). "A spearman correlation analysis indicated that both the number of CCL22+ cells and the CCL22 expression in cervical cancer cells were positively correlated with that of FOXP3+ cells (r = 0.210, p = 0.002; r = 0.144, p = 0.027, respectively)." (PMID 31842422, 2019). "We postulated that the number of CCL22+ cells or the CCL22 expression in cervical cancer cells is correlated to the number of FOXP3+ cells in cervical cancer specimens." (PMID 31842422, 2019). "In the present study, we observed the dynamic changes of CD8+ and Foxp3+ T cells in cervical cancer patients with NACT." (PMID 30474571, 2018). "In conclusion, we evaluated the effects of NACT on local CD8+ and Foxp3+ T cells in cervical cancer." (PMID 30474571, 2018). "Although further studies are needed to elucidate the molecular mechanism of Foxp3 in lymphangiogenesis of cervical cancer, the present assay will provide new insights into the lymph node metastasis of cervical cancer." (PMID 28923073, 2017). "In this study, our findings suggest Foxp3 had a significant positive correlation with VEGF-C in cervical cancer." (PMID 28923073, 2017). "This assumption was underpinned by Battaglia and co-authors and Heeren and co-authors, who showed that CD8+FoxP3+ Т cells were more frequent in metastatic tumor-draining lymph nodes in early-stage cervical cancer." (PMID 29075318, 2017). "After evaluating by two pathologists, Foxp3 expression was observed in 66% (33/50) cervical cancer tissues." (PMID 28923073, 2017). "The current study, for the first time, revealed the role of Foxp3 in lymphangiogenesis of cervical cancer." (PMID 28923073, 2017). "We studied the intranodal distribution and localization of FoxP3+ Tregs, CD8+ T cells, HLA-DR+- and PD-L1+ cells in five patients with cervical cancer by a triple FoxP3/CD8/HLA-DR immunofluorescence staining and immunohistochemical staining for PD-L1." (PMID 26431490, 2015). "This indicates that the increased expression of Foxp3 and p16INK4a may contribute as one of the mechanisms driving the occurrence and progression of cervical cancer." (PMID 38790189, 2024). "An elevated CD8/FOXP3 ratio emerges as a notable prognostic indicator for enhanced survival across diverse cancer types, including rectal cancer, esophageal squamous cell cancer, lung adenocarcinoma and cervical cancer." (PMID 39004706, 2024). "Direct binding of Foxp3 to the LINC00885 promoter can upregulate the production of proteins associated with the epithelial mesenchymal transition (EMT), thereby promoting the growth and invasion of cervical cancer cells." (PMID 38919615, 2024).